NDUFA9 (NADH:ubiquinone oxidoreductase subunit A9)
Description:
Accessory subunit of the mitochondrial membrane respiratory chain NADH dehydrogenase (Complex I), that is believed not to be involved in catalysis. Required for proper complex I assembly. Complex I functions in the transfer of electrons from NADH to the respiratory chain. The immediate electron acceptor for the enzyme is believed to be ubiquinone.
Synonyms: NDUFS2L; SDR22E1; CI-39k; COQ11; CC6; CI39k; MC1DN26
Tractability: Small molecule: an approved drug acts on it; a structure with a bound ligand is known. PROTAC: ubiquitination databases record sites on it; its protein half-life has been measured.
Gene: Protein-coding gene on chromosome 12 (4,649,095 to 4,694,317, forward strand). Ensembl gene ENSG00000139180.
Subcellular location: Mitochondrion matrix
Subcellular location (Human Protein Atlas): Mitochondria; Nucleoplasm
Pathways (Reactome):
Metabolism: Complex I biogenesis; Respiratory electron transport
Gene Ontology:
Molecular function: NADH dehydrogenase activity; protein binding; protein-containing complex binding; NADH dehydrogenase (ubiquinone) activity
Biological process: circadian rhythm; aerobic respiration; mitochondrial electron transport, NADH to ubiquinone; proton motive force-driven mitochondrial ATP synthesis; sodium ion transport; ubiquinone biosynthetic process; proton transmembrane transport
Cellular component: mitochondrial inner membrane; mitochondrial matrix; mitochondrial membrane; mitochondrion; nucleus; respiratory chain complex I
Genetic constraint (gnomAD): Loss-of-function variants: 18 observed, 34.09 expected, observed/expected ratio (o/e) 0.53, 90% interval 0.36 to 0.78. The upper end of that interval is the gene's LOEUF score, 0.78, which puts it in group 3 of 6, group 1 being the genes least tolerant of losing a copy. Missense variants: 393 observed, 430.45 expected, observed/expected ratio (o/e) 0.91, 90% interval 0.84 to 0.99. Synonymous variants: 149 observed, 150.98 expected, observed/expected ratio (o/e) 0.99, 90% interval 0.86 to 1.13.
Gene-disease validity (ClinGen):
ClinGen rates the evidence that NDUFA9 causes each of these diseases.
Leigh syndrome (autosomal recessive): Moderate. A progressive neurological disease defined by specific neuropathological features associating brainstem and basal ganglia lesions.
mitochondrial disease (autosomal recessive): Moderate.
Homologues: Orthologues: chimpanzee NDUFA9 (99% identical), dog NDUFA9 (85% identical), rabbit NDUFA9 (82% identical), pig NDUFA9 (81% identical), guinea pig NDUFA9 (80% identical), mouse Ndufa9 (78% identical), rat Ndufa9 (76% identical), tropical clawed frog ndufa9 (64% identical), zebrafish ndufa9a (58% identical), Drosophila melanogaster ND-39 (42% identical), zebrafish ndufa9b (37% identical), Caenorhabditis elegans nduf-9 (34% identical).
Diseases named in the same sentence as NDUFA9 in open-access papers:
NDUFA9 is named in the same sentence as 36 diseases in open-access papers, as found by Europe PMC text mining. Sharing a sentence is not in itself a finding about the gene and the disease. The quoted sentences say what the papers report.
Parkinson disease (3 papers, 2018 to 2023). A progressive degenerative disorder of the central nervous system characterized by loss of dopamine producing neurons in the substantia nigra and the presence of Lewy bodies in the substantia nigra and locus coeruleus. "Moreover, Parkinson’s disease (NDUFA9, TUBB4B, etc.; p-value = 4.94E-21), Prion disease (UQCR10, SDHA, etc.; p-value = 4.82E-17) and Pathways of neurodegeneration - multiple diseases (UBA52, etc.; p-value = 6.44E-16) were linked to the low abundant proteins in HF." (PMID 36891514, 2023). "NDUFA9, NDUFV2, and NDUFS3 are considered critical genes in oxidative phosphorylation and Parkinson’s disease, Huntington’s disease, and AD pathways." (PMID 35990086, 2022).
breast carcinoma (2 papers, 2023 to 2024). "Compared with the control group, OXPHOS-associated factors (NDUFA9 and SDHB) showed an obvious expression increase in YB1-silenced tumors, but the expression of HMGA1 was decreased significantly, suggesting the existence of an RNA displacement model in YB1-mediated breast cancer progression." (PMID 37035211, 2023).
Dystonia (2 papers, 2024 to 2025). An abnormally increased muscular tone that causes fixed abnormal postures. "Mutations in the NDUFA9 and NDUFAF6 genes, which are complex I assembly factors, have also been linked to dystonia." (PMID 37750949, 2024).
colorectal cancer (1 paper, 2021). A primary or metastatic malignant neoplasm that affects the colon or rectum. "For example, nuclear DNA-encoded NADH: ubiquinone oxidoreductase subunit A9 (NDUFA9) was found to be relatively upregulated in human colorectal cancer cell line SW620 and may exert a promotion effects on invasion of CRC." (PMID 34966665, 2021).
COVID-19 (1 paper, 2021). A disease caused by infection with severe acute respiratory syndrome coronavirus 2. "The Mann–Whitney U test showed significantly decreased levels in symptomatic COVID-19 compared to controls (NDUFA9: p = 0.04; SDHA: p = 0.01; COX4I1: p = 0.01)." (PMID 34679654, 2021). "Similarly, COVID-19 symptomatic cases also showed significantly lower expression levels of these genes compared to controls, together with a decrease in genes belonging to the mitochondrial respiratory chain subunits (NDUFA9, SDHA, COX4I1) and to mitochondrial dynamics (DNM1L, FIS1)." (PMID 34679654, 2021).
diabetes (1 paper, 2022). "Expressions of mitochondrial-related genes Ppargc1a (PGC1α), cytochrome b component of complex protein III (mt-Cytb), Opa1, and Ndufa9 (a component of complex protein I) were all reduced significantly by diabetes." (PMID 35133981, 2022).
glioblastoma (1 paper, 2022). The most malignant astrocytic tumor (WHO grade IV). "Alternatively, THC/CBD could reduce NDUFA9 levels in the glioblastoma cells through other mechanisms." (PMID 35804909, 2022). "Whether similar off-target effects occur in the glioblastoma cells and whether these specifically affect NDUFA9 levels remain to be investigated." (PMID 35804909, 2022). "The strong upregulation of HO-1 especially in mitochondria and the partial restoration of NDUFA9 by SnPPIX after THC/CBD treatment of glioblastoma cells demonstrated in the present study suggests that HO-1 may contribute to protein loss to some extent." (PMID 35804909, 2022).
GRACILE syndrome (1 paper, 2025). GRACILE syndrome is an inherited lethal mitochondrial disorder characterized by fetal growth restriction (GR), aminoaciduria (A), cholestasis (C), iron overload (I), lactacidosis (L), and early death (E). "All other analyzed mitochondrial proteins (NDUFA9 for complex I, SDHA for complex II, Core1 for complex III, and COX1 for complex IV) were unaffected, indicating that the loss of RISP is replicated in the iPSC-derived hepatocyte and kidney tissue models of the GRACILE syndrome." (PMID 41149808, 2025).
hepatoma (1 paper, 2020). "The NFE2L1-high/NDUFA9-low group was more enriched in EMT signature genes than the other group, implying that the NDUFA9-associated NFE2L1 expression may play a key role in hepatoma cell invasiveness." (PMID 32942643, 2020). "Thus, we asked whether the NDUFA9-associated NFE2L1 expression contributed to hepatoma cell invasiveness." (PMID 32942643, 2020). "Taken together, these results indicate that NFE2L1 is a key regulator of hepatoma cell invasiveness, and NDUFA9 depletion is an upstream driver of OXPHOS defect and NFE2L1 upregulation in HCC tumors." (PMID 32942643, 2020).
Hyperammonemia (1 paper, 2023). An increased concentration of ammonia in the blood. "Additionally, acetylation of complex I component, NDUFA9, a post translational modification that impairs protein function occurs during hyperammonemia." (PMID 37101412, 2023).
ischemia (1 paper, 2021). A hypoperfusion of the BLOOD through an organ or tissue caused by a PATHOLOGIC CONSTRICTION or obstruction of its BLOOD VESSELS, or an absence of BLOOD CIRCULATION. "The ischemia-induced reductions in protein levels of NDUFA9 and NDUFS3 were prevented by GTT treatment." (PMID 34884479, 2021). "Decreases in the activity of complex I in vehicle-treated mice subjected to ischemia were accompanied by reductions in the protein levels of subunits NDUFA9 (to 78% of sham) and NDUFS3 (to 82% of sham), but not NDUFB6." (PMID 34884479, 2021).
liver cancer (1 paper, 2020). An epithelial or non-epithelial malignant neoplasm that arises from the liver. "Our study presents a novel mitochondrial dysfunction-mediated retrograde signaling pathway and the resulting transcriptomic reprogramming in liver cancer progression, providing the NDUFA9/NFE2L1/STX12 axis as a key prognostic marker of aggressive liver cancer with mitochondrial defects." (PMID 32942643, 2020).
Obesity (1 paper, 2024). Accumulation of substantial excess body fat. "In the present study, we demonstrated that a Western-type diet can increase PFC mitochondrial respiratory complexes I (subunits NDUFS3 and NDUFA9) and II levels (FP) in a porcine model of obesity." (PMID 38397759, 2024).
oncocytomas (1 paper, 2025). "Further, we showed that a nuclear-encoded Complex I subunit, NDUFA9, was also significantly decreased in oncocytomas." (PMID 40806782, 2025).
tumor (7 papers, 2020 to 2026). "An earlier study has shown that knockdown of wild-type IDH1 triggers a set of tumor suppressor genes, including NDUFS1 (murine Ndufa9), which when mutated is implicated in low survival in certain cancers, and there is a report of high expression of WT-IDH1 in H3K27M tumors." (PMID 35395831, 2022). "Finally, in vivo xenograft studies demonstrated that NDUFA9 silencing suppressed tumor growth, corroborating the in vitro findings by inhibiting mitochondrial function, proliferation, Akt-mTOR activation, and inducing apoptosis within tumor tissues." (PMID 42014681, 2026). "OXPHOS-related proteins (e.g., ATP5F1B, NDUFA9, UQCRC2) were broadly downregulated in tumor tissues, spanning multiple core subunits of the five complexes of the mitochondrial electron transport chain, suggesting impaired mitochondrial energy production." (PMID 41480141, 2025). "At the metabolic level, key proteins in the oxidative phosphorylation pathway-such as ATP5F1B, NDUFA9, and UQCRC2—were consistently downregulated across all tumor samples, covering multiple core subunits of the mitochondrial respiratory chain complexes." (PMID 41480141, 2025). "When we monitored NFE2L1 and NDUFA9 protein levels using six paired HCC and adjacent tissue samples, four cases showed clearly increased NFE2L1 expression in tumor compared to the surrounding tissue." (PMID 32942643, 2020).
cancer (5 papers, 2016 to 2026). A tumor composed of atypical neoplastic, often pleomorphic cells that invade other tissues. "Furthermore, NDUFA9 was distinctly enriched in proliferating cancer cells and malignant epithelial cells across diverse metastatic sites." (PMID 42014681, 2026). "The most frequent cMDT disrupting interactions in over 90% of samples of a cancer type were those from the genes USP46, WDR74, RPS19, BOLA2B, NDUFA9, and LAMA3." (PMID 32879328, 2020).
neurodegenerative disease (2 papers, 2015 to 2025). A disorder of the central nervous system characterized by gradual and progressive loss of neural tissue and neurologic function. "The mitochondrial dysfunction in the neurodegenerative diseases cluster (Cluster 4) comprises 95 genes, including several key mitochondrial protein genes acting as pivotal hub genes, such as Sdhb, Ndufa4, Ndufb4c, Ndufb4b, Ndufv3, Ndufa9, Ndufc1, Ndufs5, Ndufb4, Ndufa12, Ndufa11, and Ndufb1." (PMID 41294802, 2025).
NDUFA9 also shares sentences with these, for which no sentence is quoted: Alzheimer disease (2 papers); aneurysm (2); Huntington disease (2); sleep disorder (2); abdominal aortic aneurysm (1); brain diseases (1); cardiac arrest (1); Cerebral ischemia (1); colitis (1); colorectal adenocarcinoma (1); embryonal carcinoma (1); infection (1); listeriosis (1); mitochondrial disease (1); neurological diseases (1); non-alcoholic fatty liver (1); prion disease (1); squamous cell carcinoma (1); viral infection (1).